SRC (SRC proto-oncogene, non-receptor tyrosine kinase)
Diseases named in the same sentence as SRC in open-access papers (continued):
Sharing a sentence is not in itself a finding about the gene and the disease.
Sepsis (7 papers, 2015 to 2025). Sepsis is defined as life-threatening organ dysfunction caused by a dysregulated host response to infection. "Sepecifically, we validated that Indirubin, the major bioactive metabolite of Isatidis Folium, exerts its therapeutic effects in sepsis by modulating the EGFR/SRC/PI3K and NF-κB/MAPK signaling pathways." (PMID 40144662, 2025). "Together, these results suggest a potential role for EGFR/SRC/PI3K signaling pathway in attenuating the effects of Indirubin on sepsis." (PMID 40144662, 2025). "Protein-protein interaction (PPI) network analysis revealed EGFR and SRC as the primary targets, suggesting their pivotal roles in sepsis therapy." (PMID 40144662, 2025). "Indirubin, the primary bioactive metabolite of Isatidis Folium, exerts protective effects against sepsis by targeting the EGFR/SRC/PI3K and NF-κB/MAPK signaling pathways in macrophages." (PMID 40144662, 2025). "A stable sepsis diagnostic model integrating the two most important ferroptosis markers, ATG16L1 and SRC, was constructed using a variety of machine learning models." (PMID 38780016, 2024). "Both Nissl and TUNEL staining indicated that overexpression of ATG16L1 and SRC significantly promoted the recovery of neuronal activity after sepsis and inhibited apoptosis in myocardial and lung tissues of septic rats." (PMID 38780016, 2024). "Further, some studies have also shown that inhibiting SRC activity can reduce acute lung injury and acute renal injury secondary to sepsis." (PMID 38780016, 2024). "Recent studies have reported that regulating SRC activation can improve excessive inflammation and immune collapse in sepsis." (PMID 38780016, 2024). "Based on these findings, we hypothesized that Indirubin, the primary bioactive metabolite of Isatidis Folium, exerts its anti-inflammatory effects in sepsis by modulating the EGFR/SRC/PI3K signaling pathway." (PMID 40144662, 2025). "However, we believed that the expression level of SRC can be used as a basis for early diagnosis of sepsis." (PMID 38780016, 2024). "After regulating the overexpression of specific targets, it could significantly alleviate the degree of organ damage in septic rats, further indicating that ATG16L1 and SRC function early in sepsis, and the increased expression was able to relieve sepsis." (PMID 38780016, 2024). "In addition, considering the dual biological functions of the two ferroptosis characteristic genes, ATG16L1 and SRC, it is necessary to elucidate their exact role and specific regulatory mechanisms in sepsis through in vivo and in vitro studies." (PMID 38780016, 2024). "Notably, EGFR and SRC showed the highest affinity for Indirubin, with binding energies of −9.1 and −8.9 kcal/mol, respectively, suggesting their potential as critical therapeutic targets for sepsis." (PMID 40144662, 2025). "In our prediction, SRC was found to be significantly low expressed in the tissues of sepsis patients, but previous studies believed that SRC could lead to inflammatory response through activation of immune cells, which contradict the results of our bioinformatics analysis." (PMID 38780016, 2024). "Then, network pharmacology screening revealed EGFR, PTGS2, SRC and ESR1 as the top four overlapping targets in a PPI network, and GO and KEGG analyses revealed the top 20 enriched biological processes and signalling pathways associated with the therapeutic effects of acacetin on sepsis." (PMID 34483900, 2021). "Firstly, 44 core targets of sufentanil in the treatment of acute lung injury in sepsis were discovered through network pharmacology, and key targets such as JAK2, SRC and EGFR were screened through PPI network construction." (PMID 39885929, 2024). "In the rat cecal ligation puncture sepsis model, in vivo experiments verified the involvement of ATG16L1 and SRC in the early sepsis process." (PMID 38780016, 2024).
Sepsis (continued). "GO and KEGG analyses were performed, and the core targets of EGFR, PTGS2, SRC and ESR1 were input into the Omicshare database to identify the possible mechanism by which acacetin affects sepsis." (PMID 34483900, 2021). "All potential targets of acacetin and sepsis were methodically obtained, and the top four overlapping targets in the PPI network were EGFR, PTGS2, SRC and ESR1." (PMID 34483900, 2021). "A PPI network of the 49 common targets between acacetin and sepsis was constructed based on degree value screening, and EGFR, PTGS2, SRC and ESR1 were identified as the core targets." (PMID 34483900, 2021). "Furthermore, Indirubin decreased the phosphorylation of EGFR and SRC in LPS-activated RAW264.7 cells, suggesting that its anti-inflammatory effects in sepsis are mediated through the EGFR/SRC/PI3K pathway." (PMID 40144662, 2025). "In vivo experiments in a rat sepsis model validated the differential expression of ATG16L1 and SRC." (PMID 38780016, 2024). "The upregulation of FcγR‐related genes, such as FCGR3A, FCGR1A, LYN, SYK, FYN and SRC, was detected in the prefrontal cortex, hippocampus, heart and colon of our sepsis patients, but not in the kidneys or lungs." (PMID 37731199, 2023). "From the perspective of the centrality of the PPI network, this result suggests that most of the interacting and bottleneck genes like NFKB1, SRC and MYC could have important roles in the pathogenesis of sepsis." (PMID 30297806, 2018). "HDAC4 (calcium signaling) and SRC (Wnt/β-catenin signaling) were also investigated because these genes were significantly altered in elderly individuals with sepsis compared with healthy elderly controls, and were not expressed at all in young adults." (PMID 26047321, 2015).
cardiac hypertrophy (6 papers, 2014 to 2026). "It was demonstrated that SRC kinases could be activated by Ang II, which plays an important role in Ang II-mediated processes, including the pathophysiology of cardiac hypertrophy and remodeling, vascular thickening and heart failure." (PMID 34028657, 2022).
diabetic nephropathy (6 papers, 2011 to 2025). "Wulingsan alleviates the progression of Diabetic Nephropathy by its multiple active ingredients acting synergistically on key targets such as SRC, AKT1, and TNF, thereby regulating PI3K-Akt and MAPK signaling pathways to inhibit inflammation, oxidative stress, and fibrosis." (PMID 40800999, 2025). "In an animal study, SRC activation led to collagen accumulation and the mitogen-activated protein kinase (MAPK) signaling pathway, suggesting that it might be a therapeutic target for diabetic nephropathy." (PMID 36159557, 2022).
heart failure (6 papers, 2019 to 2025). Inability of the heart to pump blood at an adequate rate to meet tissue metabolic requirements. "Some researchers believe that SRC might be a potential target for heart remodeling and heart failure." (PMID 35281886, 2022). "In addition, Istidina at the highest degree was identified in SGR via the UHPLCLTQ-Orbitrap-MSn method, and it was suggested as anti-heart failure agents by targeting SRC with molecular docking analysis." (PMID 35677443, 2022).
renal cell carcinoma (6 papers, 2017 to 2025). "For instance, the m6A methylase METTL14 was reported to negatively regulate the expression of SRC in renal cell carcinoma." (PMID 40612868, 2025). "And SRC is human proto-oncogene, which was reported as a novel therapeutic target in renal cell carcinoma." (PMID 31888623, 2019). "SRC is human proto-oncogene, which was reported as a novel therapeutic target in renal cell carcinoma." (PMID 28938536, 2017). "A similar scenario involving PTP1B elevation sensitizes renal cell carcinoma to SRC inhibition." (PMID 38089570, 2023).
renal fibrosis (6 papers, 2020 to 2025). A final common manifestation of a wide variety of chronic kidney diseases characterized by glomerulosclerosis and tubulointerstitial fibrosis. "The SRC/phosphatidylinositol 3-kinase (PI3K)/protein kinase B (Akt) signaling pathway is also critical in the pathogenesis of renal fibrosis." (PMID 41020903, 2025). "Activation of FXR has been found to attenuate renal fibrosis by inhibiting the phosphorylation of SRC, regulating the hippo pathway, and modulating the phosphorylation and localization of YAP." (PMID 37179298, 2023). "The core genes SRC, IGF1, RHOA, ESR1, EGFR and CDC42 may play a key role in the inhibition of the development and progression of renal fibrosis by diosgenin." (PMID 37179298, 2023).
acute lymphoblastic leukemia (5 papers, 2008 to 2024). Leukemia with an acute onset, characterized by the presence of lymphoblasts in the bone marrow and the peripheral blood. "c-SRC enzymes also play a vital role in hematological cancers such as CML and acute lymphoblastic leukemia (ALL)." (PMID 39459001, 2024). "Kinase profiling revealed that GNF-7 not only evidently inhibited LYN, FYN, SRC, YES, BTK and CSK kinase that can also inhibited by dasatinib, but also inhibited ACK1 and mitogen-activated protein kinase (GCK) to kill NRAS-dependent cells in AML and acute lymphoblastic leukemia." (PMID 38037057, 2023).
Alzheimer disease (5 papers, 2016 to 2023). A progressive, neurodegenerative disease characterized by loss of function and death of nerve cells in several areas of the brain leading to loss of cognitive function such as memory and language. "All this may be considered as evidence for a potential important systems biology role of SRC gene in the integral mechanism of Alzheimer’s disease." (PMID 26784894, 2016). "In the pathway unification database, SRC, EGFR, MAPT, APP and PRKCA were identified as key molecules in the pathway of Alzheimer’s disease." (PMID 37010714, 2023).
endometriosis (5 papers, 2019 to 2025). The growth of functional endometrial tissue in anatomic sites outside the uterine body. "Activated SRC is associated with an unfavorable survival in endometriosis-associated OCCC." (PMID 37087441, 2023). "Expression profiling of SRCs in endometriotic lesions identified SRC-1 as the predominant SRC in endometriosis." (PMID 31387263, 2019). "The involvement of EGFR and SRC in endometriosis has also been noted." (PMID 41239476, 2025). "Our study reported a crucial connection with protein targets such as SRC, ESR1, and PIK3 in endometriosis." (PMID 39598271, 2024).
head and neck cancer (5 papers, 2020 to 2024). A primary or metastatic malignant neoplasm affecting the head and neck. "PTPRA, an upstream phosphatase of SRC is reported for its oncogenic role and is highly expressed in head and neck cancers." (PMID 36393868, 2022). "SRC inhibitors have been shown to reduce MDSCs in head and neck cancer and improve overall survival." (PMID 32419823, 2020).
hyperlipidemia (5 papers, 2016 to 2024). "Inhibition of SRC activation has been observed to reduce endogenous ROS production and increase ATP production in diabetic mice with hyperlipidemia." (PMID 37985432, 2024). "Inhibition of SRC(c-Src) activation was found to decrease endogenous ROS production and increase ATP production in diabetic mice with hyperlipidemia." (PMID 34028657, 2022).
metastatic tumors (5 papers, 2008 to 2023). "Together, our findings uncover a conserved Yki/YAP-Src42A/SRC positive feedback loop promoting tumor cell migration and provide SRC as a potential therapeutic target for YAP-driven metastatic tumors." (PMID 34862372, 2021). "It is well known that GC with PD/SRC usually has worse outcomes than other pathologic types, especially in advanced stages and metastatic disease." (PMID 32842507, 2020). "Moreover, decreased levels of SRC expression were strongly associated with induced expression of AR pathway gene signatures by GSEA in the Taylor PCa dataset, which is composed of gene expression data from the tissue specimens of 111 PCa patients, including 98 primary and 13 metastatic tumors." (PMID 27028864, 2016).
multiple myeloma (5 papers, 2017 to 2025). "A study demonstrated that crocin can mediate the suppression of STAT3 and inhibit the upstream kinases JAK1, JAK2, and SRC, thereby preventing the progression of multiple myeloma." (PMID 40841966, 2025).
psoriasis (5 papers, 2023 to 2025). An autoimmune condition characterized by red, well-delineated plaques with silvery scales that are usually on the extensor surfaces and scalp. "KX2-391, also known as Tirbanibulin, is a novel selective SRC inhibitor and has been approved for treating actinic keratosis and psoriasis." (PMID 36923538, 2023). "Additionally, sustained SRC over-expression can induce cellular transformation with the potential to induce hyperproliferative keratinocytic disorders, e.g., psoriasis, but also malignant skin tumors including cSCC." (PMID 38847867, 2024). "Interestingly, targeting SRC and members of its family has been explored in treating psoriasis." (PMID 40560578, 2025). "The expression of SRC and RAPGEF1 was further investigated in pathologies exhibiting keratinocyte hyperproliferation and involving miR-203, such as psoriasis and NMSC." (PMID 37635193, 2023). "As miR-203 is also involved in skin diseases where keratinocytes are hyperproliferating, such as psoriasis and NMSC, BCC and SCC, this raised the question of the role of SRC and RAPGEF1 in these pathologies." (PMID 37635193, 2023). "We could then hypothesize that SRC and RAPGEF1 could participate in keratinocyte hyperproliferation in psoriasis." (PMID 37635193, 2023).
colorectal tumors (4 papers, 2002 to 2023). "Overall, our study demonstrates that SRC signaling is at the nexus of a cell-autonomous inflammatory program with pro-tumorigenic activities, which explains why BRAFV600E colorectal tumors develop resistance to BRAF/MEK and EGFR inhibitors." (PMID 36759733, 2023). "COX2 levels were similar in untreated primary patient colorectal tumor specimens with or without a BRAFV600E mutation, again corresponding to observations with SRC." (PMID 36759733, 2023).
HIV-1 infection (4 papers, 2017 to 2023). The type species of lentivirus and the etiologic agent of acquired immunodeficiency syndrome (AIDS). "There are several models for humanized mice with different strains of mice and different engraftment methods that have been utilized to study HIV-1 infection, including the Hu-PBL-SCID, Hu-SRC-SCID, NSG, NRG, TKO-BLT, and BLT mice." (PMID 29163484, 2017). "In contrast, a study investigating whether STKIs—including dasatinib—exerted their inhibitory effect on HIV-1 infection through the interaction between c-SRC and its ligand PTK2B concluded that multiple postentry steps played a major role in blocking HIV-1 infection." (PMID 31619990, 2019).
kidney cancer (4 papers, 2021 to 2025). Primary or metastatic malignant neoplasm involving the kidney. "Applying a high-throughput drug screen to multiple human kidney cancer cells, we identify the combination of the VEGFR-MET inhibitor cabozantinib and the SRC inhibitor dasatinib acts synergistically in cells to markedly reduce cell viability." (PMID 34095877, 2021). "P300‐activated JMJD6 may constitute SEs to drive a series of kidney cancer‐related drivers, such as VEGFA, β‐catenin, or SRC." (PMID 33634984, 2021). "Particularly, high‐throughput sequencing data revealed that JMJD6 could assemble super‐enhancers to drive a list of identity genes in kidney cancer, including VEGFA, β‐catenin, and SRC." (PMID 33634984, 2021).
liver cirrhosis (4 papers, 2015 to 2023). "Changes in c-SRC activation in models of experimental liver damage mirrored the situation in human liver cirrhosis." (PMID 26696895, 2015). "SRC expression varies dramatically depending on the stage of liver cirrhosis." (PMID 36297027, 2022). "The focal adhesion pathway encompasses several genes, and KEGG analysis demonstrated that AKT1, CTNNB1, EGFR, FN1, JUN, and SRC were strongly related to curcumin compounds that might be influenced by liver cirrhosis in our study." (PMID 36297027, 2022). "Also in experimental models of toxic liver cirrhosis levels of total c-SRC remained unchanged, while RhoA was significantly increased." (PMID 26696895, 2015). "Other research suggests that liver cirrhosis might be attenuated by using SRC inhibitors." (PMID 36297027, 2022). "Since this crosstalk of RhoA and c-SRC could be observed in cholestatic and toxic models of liver cirrhosis, as well as in alcohol-induced human liver cirrhosis, our data suggest that the mechanisms are independent of the etiology." (PMID 26696895, 2015).
ovarian tumors (4 papers, 2015 to 2020). "SRC tyrosine kinase is frequently overexpressed and activated in late-stage, poor prognosis ovarian tumours, and preclinical studies have supported the use of targeted SRC inhibitors in the treatment of this disease." (PMID 29435137, 2018). "Distinction from a primary ovarian tumor can be difficult because some primary ovarian tumors can also contain SRC." (PMID 26612593, 2015).
prostate adenocarcinoma (4 papers, 2018 to 2022). "Increased levels of phosphorylated CAV1 and SRC were even found within malignant epithelial cells of advanced human prostate adenocarcinomas." (PMID 35155239, 2022).
skin squamous cell carcinoma (4 papers, 2014 to 2020). A carcinoma arising from the squamous cells of the epidermis. "Furthermore, topical application of the PPARβ/δ antagonist GSK0660 prevented UV-dependent Src stimulation; and the expression of PPARβ/δ positively correlated with the expression of SRC and EMT markers in human skin squamous cell carcinoma (SCC) highlighting the clinical relevance of these findings." (PMID 32375405, 2020).
acute myeloid leukemia (3 papers, 2018 to 2025). Acute myeloid leukemia (AML) is a group of neoplasms arising from precursor cells committed to the myeloid cell-line differentiation. "For example, activated tyrosine kinase SRC interacts with motifs on Akt-mTOR in acute myeloid leukemia (AML) cells, a process which upregulates signaling and stemness in AML." (PMID 29518044, 2018).
adenoma (3 papers, 2002 to 2021). A neoplasm arising from the epithelium. "In CRC, SRC deregulation was found in 80% of cases, with increasing SRC activity along the adenoma-carcinoma sequence from normal mucosa and colonic polyps to distant liver metastases." (PMID 23900414, 2013).
autoimmune disease (3 papers, 2021 to 2023). A disorder resulting from loss of function or tissue destruction of an organ or multiple organs, arising from humoral or cellular immune responses of the individual to their own tissue constituents. "Importantly, loss or gain of function of JAK1 and SRC caused by rare mutations has been reported to trigger combined immunodeficiency, cancer progression, or autoimmune disease in human patients." (PMID 36329033, 2022). "Our research reveals the potent therapeutic effect of costunolide in AIH and the potential role of SRC and IGF1R in AIH for the first time, which may further contribute to the novel drug development for AIH and other autoimmune diseases." (PMID 37163367, 2023). "SRC can participate in the process of cell differentiation, proliferation, and apoptosis through the MAPK signaling pathway and plays a crucial role in the inflammation and autoimmune diseases." (PMID 34873575, 2021).